MIR6769A (microRNA 6769a)
Synonyms: hsa-mir-6769a
Gene: MicroRNA gene on chromosome 16 (4,671,318 to 4,671,390, forward strand). Ensembl gene ENSG00000276641.
Homologues: Orthologues: chimpanzee MIR6769A (100% identical).